CCL2 (C-C motif chemokine ligand 2)
Diseases named in the same sentence as CCL2 in open-access papers (continued):
Sharing a sentence is not in itself a finding about the gene and the disease.
hepatocellular carcinoma (continued). "Hox antisense intergenic RNA overexpression in hepatocellular carcinoma cell lines Li-7 and Hep3B led to an increase in CCL2 expression in these cells." (PMID 31921102, 2019). "The neutralizing antibody against CCL2 was also found to suppress hepatocellular carcinoma in a mouse model by enhancing NK cell cytotoxicity and IFN-γ production in the liver." (PMID 31555577, 2019). "MCP-1 (CCL2) has been successfully used to treat hepatocellular carcinoma by recombinant adenovirus vector (rAd)s expressing with HSV-tk." (PMID 22971726, 2012). "Hepatic myofibroblasts have been shown to secret CCL2 to promote migration and invasion of hepatoma cells." (PMID 21826248, 2011). "Additionally, in HrasG12V‐mutated hepatocellular carcinoma (HCC), senescent HCC cells secrete SASP factors (such as CCL2, IL‐15 and CXCL1) that activate macrophages, neutrophils and NK cells, thereby mediating innate immunity and suppressing tumour progression." (PMID 39270064, 2024). "CCL2 stimulates immature circulating myeloid cells to differentiate into infiltrating macrophages that can subsequently clear senescent cells, and ablation of CCL2 led to hepatocellular carcinoma outgrowth." (PMID 39000121, 2024). "Moreover, CCL2 plays a key role in the elimination of senescent cancer cells in liver carcinoma mostly by driving NK cell recruitment to the tumor." (PMID 38561826, 2024). "In addition, CCL2 in hepatocellular carcinoma (HCC) models attracts CCR2+ myeloid cells that stimulate SC clearance via immunosurveillance but can promote the growth of already established HCC cells by inhibiting NK cell–mediated clearance of cancer cells." (PMID 35775492, 2022). "Thus, we alternatively stimulated HepG2 cells (human hepatoma cell line) with Pg-derived LPS or human recombinant IL-1β as positive control and examined mRNA expressions of CCL2, CXCL10, and FOXO1 using real time PCR." (PMID 34526589, 2021). "On the other hand, studies demonstrated the beneficial effects of SASP components in the clearance of senescent cells, such as CCL2 secretion by senescent tumor cells in liver carcinoma which induces NKG2D ligand expression on tumor cells to activate NK-mediated clearance through NKG2D." (PMID 32570952, 2020). "Thus, in models of hepatocellular carcinoma, early stages of senescent precancerous hepatocytes secrete CCL2 via their SASP which acts as a tumor suppressive mechanism promoting the recruitment of macrophages to remove senescent cells." (PMID 32570952, 2020). "Furthermore, the upregulation of this gene, as well as CCL2, IL6, and LOXL2, has been implicated as part of the effects of cancer-associated fibroblasts in promoting progression of hepatocellular carcinoma cells." (PMID 32154227, 2020). "Furthermore, the relevance of these findings was also confirmed in human hepatocellular carcinoma tumor tissue stainings, where CCL2 expression in tumor cells correlated with the tumor-infiltrating CD68+ TAM and lower numbers of antitumorous CD8+ T cells." (PMID 31921102, 2019). "Interestingly, in a recent study hepatocellular carcinoma cells expressing FoxQ1 were shown to increase recruitment of macrophages through CCL2 production." (PMID 29203829, 2017). "Similarly, CCL2-induced human hepatoma cell migration and invasion has been blocked by anti-syndecan-1 and -4 antibodies, but also when hepatoma cells were pretreated with heparitinases that remove glycosaminoglycans from cell surfaces." (PMID 22505933, 2012). "Sorafenib is a treatment for hepatocellular carcinoma (HCC) that enhances its anticancer effects by inhibiting CCL2 and CCL17 transcriptional regulators in neutrophils." (PMID 41451221, 2025). "In addition, a more recent study showed that blocking the MCP1 (CCL2)-CCR2 interaction with a CCL2-neutralizing antibody in a murine hepatocellular carcinoma model reduced the number of inflammatory myeloid cells (CD11highGr1+) and increased the cytotoxicity of hepatic NK cells." (PMID 40430040, 2025).
hepatocellular carcinoma (continued). "A study on hepatocellular carcinoma found that SLFN11 deficiency can enhance the infiltration of immunosuppressive macrophages and promote their transformation to the M2-like phenotype by activating the Ccl2 signaling pathway, thereby exacerbating tumor progression." (PMID 41562082, 2025). "In hepatocellular carcinoma (HCC) cells, Drp1-dependent division aguments mtDNA stress and thus enhances the secretion of CCL2 via the TLR9-involved NF-κB pathway." (PMID 37497006, 2023). "In addition, CCL2 could also induce TANs to express PD-L1, which inhibited tumor immunity in hepatocellular carcinoma." (PMID 36077785, 2022). "Moreover, the recruitment of macrophages and Tregs via CCL2 secretion could be suppressed by p38 inhibition in hepatocellular carcinoma, thus inhibiting tumor growth and metastasis." (PMID 35647201, 2022). "In hepatocellular carcinoma (HCC), CCL2 elevated PD-L1 expression by activating the NF-κB pathway." (PMID 41341593, 2025). "In hepatocellular carcinoma (HCC), The indirect co-culture system revealed that TAMs released more CCL2 into the culture medium when they were cultured with HCC cells than when they were cultured alone." (PMID 41341593, 2025). "CCL2 is prognostic for hepatocellular carcinoma (HCC), where targeting TAMs via CCL2/CCR2 blockade effectively reduces tumour growth, reverses the immunosuppressive TME, and enhances cytotoxic T-cell responses." (PMID 40683913, 2025). "Intriguingly, the expression levels of ASH1L, CCL2, and CSF1 further decreased in hepatoma cells if ASH1L was simultaneously knocked down in the cocultured HSCs, and vice versa (data not shown)." (PMID 39377228, 2024). "In hepatocellular carcinoma (HCC), CD66b + TANs exhibited increased expression of TNF-α, IL-8, CCL2 and cell-death ligand 1 (PDL1) and decreased CD62L expression." (PMID 37212866, 2023). "FOXC1 upregulates the expression levels of CCL2 and CXCR1 by directly binding to their promoters in hepatocellular carcinoma cells." (PMID 33968763, 2021). "In hepatocellular carcinoma (HCC) tissues, CAFs secrete CCL2 and CCL5 and induce metastasis by activating the hedgehog pathway." (PMID 34445235, 2021). "In hepatocellular carcinoma (HCC), TAMs are recruited by cancer cells by expressing glypican and secrete TGF-β, PDGF, VEGF, chemokine (C-C motif) ligand 2 (CCL2), and M-CSF." (PMID 33922795, 2021). "IL-8 activates FoxC1 expression via the PI3K/AKT pathway and via hypoxia-inducible factor 1 alpha, and FoxC1 expression induces CXCR1 and CCL2 transactivation and promotes inflammation in hepatocellular carcinoma (HCC) and the migration and invasion of HCC cells." (PMID 32373221, 2020). "A recent report showed a reduction of CCL2/CCR2 signaling inhibited macrophage infiltration and M2-polarization in hepatocellular carcinoma." (PMID 33156861, 2020). "In mouse models, TANs mediate the infiltration of regulatory T (Treg) cells and macrophages in the TME by secreting the chemokines CCL2 and CCL17, leading to the growth of hepatocellular carcinoma cells and increasing the resistance of hepatocellular carcinoma patients to sorafenib." (PMID 36324574, 2022). "For example, YAP activation is associated with TAM recruitment and M2 phenotype polarization, leading to a pro-tumorigenic or immune suppressive environment, potentially via C-C motif chemokine ligand 2 (CCL2 or MCP1) activation, as shown in hepatocellular carcinoma." (PMID 34572875, 2021). "Studies revealed that mice lacking expression of this miRNA showed an increase in lipogenesis, lower serum cholesterol/triglyceride levels, fibrosis enhancement, NASH, and hepatocellular carcinoma, in addition to increased expression of TNF‐α, IL-6, and C-C motif chemokine ligand 2 (CCL2) genes." (PMID 34426744, 2021).
hepatocellular carcinoma (continued). "Consistently, in human hepatocellular carcinoma tissues, TANs expressed abundantly CCL17 and CCL2, which could attract Tregs and macrophages, respectively, and depletion of neutrophils enhanced the sensitivity to sorafenib in mouse HCC models, as evidenced by reduced tumor growth." (PMID 32422991, 2020). "In hepatocellular carcinoma (HCC), FOXC1 facilitates C-C motif chemokine ligand 2 (CCL2) or C-X-C motif chemokine receptor 1 (CXCR1) expression to drive tumor-associated macrophage infiltration and metastasis." (PMID 40416363, 2025). "During the development of hepatocellular carcinoma (HCC), chemokine CCL2, another SASP factor, recruits immature suppressive myeloid cells that inhibit NK cell function and promotes the progression of HCC." (PMID 37090726, 2023). "It was highlighted that TANs, but not circulating neutrophils, via the production of CCL2 and CCL17 and the recruitment of monocytes and Treg cells, were the cause of the refractoriness to sorafenib, the first line treatment for hepatocellular carcinomas (HCC)." (PMID 35664746, 2022). "The model features consisted of three assays: CCL2 down-regulation in a complex coculture of peripheral blood mononuclear cells and endothelial cells, CD40 down-regulation in the same system, and a cell viability assay in the HepG2 human hepatocellular carcinoma cell line." (PMID 21788198, 2011). "In hepatocellular carcinoma (HCC), LPS promotes cell survival, proliferation, invasion, and production of pro-inflammatory mediators, including TNF-α, iNOS, IL-1β, IL-6, CCL-2, CCL-22, vimentin, and epidermal growth factor receptor (EGFR), through the induction of TLR4 signaling." (PMID 40444051, 2025). "Studies have shown that inhibition of CCL2 reduces bone marrow monocyte infiltration and TAM polarization, thereby slowing down tumor growth in various cancers, such as lung cancer, bladder cancer, and hepatocellular carcinoma (HCC)." (PMID 39169402, 2024). "Evidence from hepatocellular carcinoma (HCC) showed that both gene ablation and pharmacological inhibition of DPP-4 notably prevent tumor progression by down-regulating the production of chemokine CCL2." (PMID 35933633, 2022). "Importantly, CCL2, CCL5, and CXCL10 have been described in the process of conversion of senescent premalignant cells mediated by oncogenes activation that could culminate with hepatocellular carcinoma." (PMID 32784775, 2020).
glioblastoma (117 papers, 2005 to 2025). The most malignant astrocytic tumor (WHO grade IV). "Kaplan–Meier analysis of 540 glioblastoma cases from the Glioblastoma tumor RNA-Sequence dataset we identified showed a negative association between levels of gene expression of IL-4, IL-10, CCL-2, GM-CSF, and VEGF and overall survival." (PMID 35884700, 2022). "Accumulation of CCL2 was found to be correlated to poor prognosis in glioblastoma patients, whereas deficiency of CCL2 reduced the recruitment of MDSCs and Treg cells in a glioblastoma mouse model." (PMID 31620141, 2019). "Freshly resected glioblastoma tissue synthesizes and secretes CCL2, a chemokine also associated with the recruitment of Treg." (PMID 20691089, 2010). "High expression of CCL2 in glioblastoma patients is associated with poor survival." (PMID 34503065, 2021). "In addition, CCL2 inhibition by mNOX-E36 combined with bevacizumab exerted a suppressing effect on the recruitment of tumor-associated macrophages and angiogenic processes in a rat glioblastoma model." (PMID 36980182, 2023). "CCL2 is the only chemokine detected in glioblastoma tissue by enzyme-linked immunosorbent assay, indicating that CCL2 may be the principal chemokine for Treg migration to glioblastoma tissue." (PMID 20691089, 2010). "A 25-plex ELISA, measuring 23 of the 34 cytokines we consider here, showed that ZIKV infection only significantly increased CXCL10 and CCL5 secretion and decreased CCL2 secretion from adult glioblastoma cells." (PMID 40240536, 2025). "Silencing IRF8 in glioblastoma stem cells reduces CCL2 expression, significantly weakening the immune evasion capability of CSCs and directly confirming the pro-oncogenic role of IRF8 in these cells." (PMID 41368628, 2025). "Specifically, HSPCs were identified within the glioblastoma tumor microenvironment, further promoting glioblastoma cell proliferation and secreting pro-metastatic factors such as IL-6 and CCL2, alongside increased PDL1 expression by cancer cells." (PMID 40822347, 2025). "Human CCL2 is a well-known macrophage chemoattractant that is expressed at higher levels in mesenchymal subtype glioblastoma." (PMID 40610434, 2025). "PriGO17A cells have increased expression of CCL2 mRNA and secrete high levels of CCL2 protein relative to three predominantly classical subtype glioblastoma cell cultures isolated from different patients under identical conditions." (PMID 40610434, 2025). "Glioblastoma cell-derived EVs upregulated the expression of the pro-tumor genes in microglia cells, including the CXCL1/10, CCL2/CCL5, and IL-6, and downregulated immune response-associated genes, such as IL-16, IL-23, and IL-2740." (PMID 39781357, 2025). "As a primary approach in treating glioblastomas, radiotherapy can upregulate the expression of monocyte chemokine-1 (MCP-1)/C-C basal chemokine ligand 2 (CCL-2) in the tumor region, promoting the chemotaxis of monocytes." (PMID 38615157, 2024). "A different research group reported an alternative mechanism behind CCL2 modulation of glioblastoma growth." (PMID 38786066, 2024). "To further confirm the role of glioblastoma cell CCL2 and CCL7 in macrophage infiltration, we first employed shRNAs to deplete CCL2 and CCL7 in CT2A and GL261 cells." (PMID 38443336, 2024). "IL-10 increased secretion in the glioblastoma microenvironment has the effect of amplifying the release of other anti-inflammatory cytokines such as IL-4 and Chemokine C-C motif ligand 2 (CCL2)." (PMID 38391974, 2024). "Combined profiling and functional studies demonstrate that LDHA-directed ERK pathway activates YAP1/STAT3 transcriptional co-activators in glioblastoma cells to upregulate CCL2 and CCL7, which recruit macrophages into the tumor microenvironment." (PMID 37886538, 2023). "CCL2 is one of the most important chemoattractants and was originally isolated from a human glioblastoma cell line." (PMID 37705736, 2023).
glioblastoma (continued). "CCL2 can increase the metastasis and invasiveness of breast, intestinal, lung tumors, and glioblastoma multiforme." (PMID 38180104, 2023). "CCL-2 blockade reduces the percentage of migratory glioblastoma cells upon biopsy below that observed for control and clodronate-liposome-treated mice." (PMID 35883641, 2022). "Glioblastoma tumors also have substantial Treg populations; these are recruited either directly via glioblastoma cell secretion of chemokines such as CCL2, or indirectly by chemokine signaling from infiltrated myeloid cells." (PMID 33753869, 2022). "The CCL2 inhibitor mNOX-E36 inhibits the recruitment of M2-like TAMs and improves antiangiogenic treatment for glioblastoma in rats." (PMID 36679900, 2022). "In some experimental glioblastoma models, tumor cells released CCL2 to attract macrophages, and CCL2/CCR2 blockade prolonged mouse survival." (PMID 35600367, 2022). "M2-polarized microglia suppressed phagocytosis and promoted the growth of the irradiated glioblastoma cells by CCL2/CCR2 axis." (PMID 36058942, 2022). "Pharmacological β-catenin inhibition with MSAB reduces Wnt/β-catenin activity and induces apoptosis in glioblastoma cells, while altering CCL2 secretion." (PMID 35562953, 2022). "β-catenin and CCL2 are important determinants of monocyte attraction towards glioblastoma cells and show interdependence in vitro." (PMID 35562953, 2022). "CCX872, another CCL2 antagonist, efficiently reduces tumor-associated MDSCs, which are converted into TAMs in the TME, thereby improving survival in animal models of glioblastoma." (PMID 36679900, 2022). "In a rat model of glioblastoma, the CCL2 inhibitor mNOX-E36 inhibits the recruitment of M2-like TAMs and improves the antiangiogenic treatment of glioblastoma." (PMID 35672862, 2022). "The CCL2/CCR2/CCR4 pathway exerts immunomodulatory effects on glioblastoma through the recruitment of CCR2+ GAMs, CCR2+ MDSCs and CCR4+ Tregs, and these immunosuppressive cells can contribute to immune escape by attenuating the effector T cell response." (PMID 33803414, 2021). "CD133+ glioblastoma stem cells induce hUCMSC migration to tumor regions by secreting CCL2 and CXCL12." (PMID 33849537, 2021). "For example, combination therapy with bevacizumab and CCL2 inhibitor, mNOX-E36, decreased the recruitment of TAMs and angiogenesis, resulted in decreased tumor volume and blood volume in CCL2-expressing rat glioblastoma multiforme model." (PMID 34209679, 2021). "Meningiomas express several factors, which are known to have chemotactic properties on microglia in glioblastoma multiforme (e.g., CCL2, CX3CL1, SDF-1, G-CSF and GM-CSF)." (PMID 34503077, 2021). "In a rat glioblastoma model, TAMs recruitment was blocked after the administration of CCL2 inhibitor, thus reducing angiogenesis and inhibiting tumour growth." (PMID 34464477, 2021). "CCL2 expression is significantly higher in glioblastoma patient tumour samples and cell lines compared to healthy brain tissue, and its gene expression has a negative correlation with overall survival of patients." (PMID 33803414, 2021). "Another chemokine engaged in primary brain tumor pathogenesis is chemoattractant protein 1 (CCL2/MCP-1), a high expression of which was found in glioblastoma, anaplastic astrocytoma, and World Health Organization (WHO) grade 2 fibrillary astrocytoma." (PMID 32886667, 2020). "Second, we performed a survival analysis study to evaluate the benefit of mNOX-E36 in a CCL2-expressing tumor animal model, thus in future applications of our results, it will be helpful for selected candidates with high CCL2-expressing glioblastomas." (PMID 31366997, 2019).